PRPH (peripherin)
Diseases named in the same sentence as PRPH in open-access papers (continued):
Sharing a sentence is not in itself a finding about the gene and the disease.
autosomal dominant retinitis pigmentosa (1 paper, 2011). Autosomal dominant retinitis pigmentosa (RP) is an autosomally dominant inherited retinal dystrophy leading to progressive loss of the photoreceptors and retinal pigment epithelium and resulting in blindness usually after several decades. "The RDS gene located on chromosome 6p21.1-cen encodes for the protein peripherin, or RDS/Peripherin, and is responsible for an estimated 5-10% of autosomal dominant retinitis pigmentosa." (PMID 22131872, 2011).
axonal neuropathy (1 paper, 2020). Any nerve disorder affecting the axon of a nerve. "Immunohistochemical study for peripherin in association with anti-MBP and anti-NF-H antibodies showed a markedly increased expression of peripherin and NF-H in the proband compared to a CMT2A patient (MFN2R94W, axonal neuropathy control) and a healthy control." (PMID 32326241, 2020).
central areolar choroidal dystrophy (1 paper, 2007). "Different phenotypes, including central areolar choroidal dystrophy (CACD), adult vitelliform macular dystrophy (AVMD), and pattern macular dystrophy (PMD) were found for these peripherin/RDS mutations." (PMID 17653047, 2007).
colorectal cancer (1 paper, 2022). A primary or metastatic malignant neoplasm that affects the colon or rectum. "In colorectal cancer, PTN may play a role as the downstream of PRPH and promote tumor progression." (PMID 35281077, 2022).
cone-rod dystrophy (1 paper, 2018). Inherited retinal dystrophies that belong to the group of pigmentary retinopathies. "Specifically, Sanger sequencing of ABCA4, PRPH2/RDS-peripherin, and ELOVL4 was negative except for Proband 1, who had a heterozygous ABCA4 missense variant (c.2588G>C; p.Gly863Ala) and no family history of Stargardt disease or cone-rod dystrophy." (PMID 30116628, 2018).
deafness (1 paper, 2023). An inherited or acquired condition characterized by the complete loss of the ability to hear from one or both ears. "The current work found a series of DEGs related to sensory epithelial development and cytoskeleton organization through functional enrichment and PPI network analysis, including ATOH1, VIM, PRPH and NEFL, which may be involved in the pathogenesis of ELMOD3 causing deafness." (PMID 37708136, 2023).
endometriosis (1 paper, 2017). The growth of functional endometrial tissue in anatomic sites outside the uterine body. "TRPV1-immunoreactivity was increased in small, peripherin-positive, nociceptive neurons in DRG of mice with endometriosis and EP2 expression was further increased in these cells." (PMID 28281561, 2017).
glaucoma (1 paper, 2023). Increased pressure in the eyeball due to obstruction of the outflow of aqueous humor. "Furthermore, additional genes can also exacerbate non-neurodegenerative disease phenotypes, such as glaucoma (optineurin, OPTN), Enterovirus-induced Type-1 diabetes (Peripherin, PRPH), leukemia, or cancer (TATA-box-binding protein-associated factor 15, TAF15)." (PMID 37566027, 2023).
hepatocellular carcinoma (1 paper, 2022). A malignant tumor that arises from hepatocytes. "Interestingly, peripherin has been detected as 1 of 13 novel tumor suppressor candidate genes silenced by DNA methylation in hepatocellular carcinoma (HCC)." (PMID 36499746, 2022).
lung carcinoma (1 paper, 2020). "The methylation status of RASSF1A, CDH1, DLC1 and PRPH was analysed in BW samples from 91 lung cancer patients and 31 controls, using a novel two‐colour droplet digital methylation‐specific PCR (ddMSP) technique." (PMID 32441866, 2020).
malignant melanoma (1 paper, 2014). "The present case report clearly demonstrated that intermediate filaments, including cytokeratin, peripherin, α-internexin, GFAP and nestin, were not expressed in the signet-ring cell melanoma, although, peripherin and nestin are commonly expressed in malignant melanoma." (PMID 24348822, 2014).
multiple sclerosis (1 paper, 2023). A progressive autoimmune disorder affecting the central nervous system resulting in demyelination. "This may explain why some patients with multiple sclerosis have higher levels of peripherin, as these patients have spinal cord lesions and are likely to have damaged anterior horn cells or dorsal column axons." (PMID 37435933, 2023).
neuritis (1 paper, 2012). A neuropathy arising from inflammation of one or more nerves. "The importance of peripherin in this development has been highlighted by a research study that observed that depletion by peripherin-siRNA inhibited the initiation, extension, and maintenance of neuritis." (PMID 22474509, 2012).
proteinopathy (1 paper, 2024). "IMS-088 was effective in mitigating TDP-43 proteinopathy and formation of peripherin aggregates in mice infused with CSF from sporadic ALS." (PMID 38790979, 2024).
rhabdoid tumor (1 paper, 2021). An aggressive malignant embryonal neoplasm usually occurring during childhood. "The LM F2T2↑ rhabdoid tumor showed a massive upregulation of a unique growth factor program with selectively activated Wnt and SHH/ciliogenesis pathways, and an intermediate filament expression switch, with GFAP loss, and peripherin and vimentin massive overexpression." (PMID 33853673, 2021).
Sensory axonal neuropathy (1 paper, 2025). An axonal neuropathy of peripheral sensory nerves. "Serum peripherin concentrations were elevated in all patients with MND compared to healthy controls, with particularly higher levels observed in patients with Spinal and Bulbar Muscular Atrophy, likely due to the concomitant sensory axonal neuropathy commonly found in this patient group." (PMID 39995075, 2025).
tumor (7 papers, 2012 to 2023). "Similar to these studies, we also reported that PRPH was positively associated with tumor-associated macrophages." (PMID 33833937, 2021). "Since promoter methylation may cause transcriptional silencing of the gene and advanced NB tumor stages are less differentiated, this is in line with the idea that high levels of peripherin contribute to more differentiated tumor stages." (PMID 23034519, 2012). "CD133+ human umbilical hematopoietic progenitor cells were revealed to promote the proliferation and invasion of CRC cells in vitro and enhance tumor growth and metastasis in vivo by upregulating PRPH." (PMID 33833937, 2021). "As demonstrated in this study, this idea is further strengthened by the fact that PRPH mRNA expression levels gradually decreased with increasing aggressiveness of the tumor." (PMID 23034519, 2012). "Their expression is consistent with the large field-of-view data, with PYGL and PRPH showing opposite expression patterns across the margin between solid tumour (high PYGL, low PRPH) and brain/tumour interface (low PYGL, high PRPH) and haemoglobin co-localising with the visible blood vessels." (PMID 38001067, 2023). "In our study, PRPH methylation was mainly detected in more advanced tumor stages." (PMID 23034519, 2012). "Peripherin is an intermediate filament protein without a clear function and is highly expressed during development and after nerve injury; its expression pattern is consistent with the tumour growth into surrounding normal brain tissue." (PMID 38001067, 2023).
peripheral neuropathy (6 papers, 2013 to 2025). A disorder affecting the peripheral nervous system. "The fact that RAB7A could regulate peripherin assembly and thus peripherin functions reveals a new mechanism that may potentially explain the peripheral neuropathy caused by RAB7A mutations." (PMID 23179371, 2013). "ZFHX2 has enriched expression within DRGs, particularly within the peripherin positive population of neurons, and so we investigated if the pain insensitive phenotype was due to a peripheral neuropathy." (PMID 29253101, 2018).
cancer (4 papers, 2020 to 2023). A tumor composed of atypical neoplastic, often pleomorphic cells that invade other tissues. "The role of PRPH in cancer is less clear: it encodes the cytoskeletal protein peripherin, a type III intermediate filament with homology to other cytoskeletal proteins such as desmin, and that is found in neurons of the peripheral nervous system." (PMID 32441866, 2020). "And most of the 24 DEPs (CDK1, SFN, PRKAR2B, MKI67 and MDK involved in the cell cycle; LOXL2, P4HA1, P4HA2, SPRX, DES, PRPH and CALML3 involved in construction and regulation of extracellular matrix; IL33 and EHD3 may involve in immune) were linked to cancer hallmarks." (PMID 33200655, 2020). "Moreover, at the multi-cancer level, known cancer drivers such as CDC45 and NUF2 were identified to be involved in edgetic gains while NTRK1, PRPH and MYOC were determined to be involved in edgetic losses and may serve as targets for widely applicable therapeutic interventions." (PMID 32152446, 2020).
neurodegenerative disease (4 papers, 2012 to 2025). A disorder of the central nervous system characterized by gradual and progressive loss of neural tissue and neurologic function. "Dysregulation of peripherin and its splice variants has been associated with the neurodegenerative disease ALS." (PMID 26694421, 2015). "In our study, α-Internexin- and peripherin-overexpressing PC12 cells (pINT-EGFP and pEGFP-peripherin) were used as models to study neuropathological pathways responsible for neurodegenerative diseases." (PMID 22952800, 2012). "In our earlier work, the pEGFP-Peripherin and pINT-EGFP cell models were used to study neuropathological pathways responsible for neurodegenerative diseases." (PMID 22952800, 2012). "Since peripherin is expressed in the neurons of the PNS, the modulation of peripherin amount or function could promote the onset of neurodegenerative diseases, many of which are characterized by alterations in the endocytic and autophagy pathways." (PMID 39859265, 2025).
neurological disease (4 papers, 2014 to 2025). "With this foundation, the authors documented that the peak levels of peripherin were higher in patients with GBS compared to those with other neurological diseases and healthy controls." (PMID 39995075, 2025). "The most important study exploring the role of peripherin as biomarker in neurological diseases was recently published by Keddie and colleagues." (PMID 39995075, 2025). "Despite less attention being paid to NfM, INA and PRPH as biomarkers in neurological diseases, their potential utility is considerable." (PMID 34646114, 2021). "In this respect, overexpression of several intermediate filaments including glial fibrillary acidic protein, peripherin or neurofilaments in mice has been shown to be toxic, leading to neurological disorders affecting the respective organs." (PMID 25617501, 2015). "The aim of this systematic literature review is to consolidate current knowledge on peripherin by emphasizing its unique characteristics, highlighting its potential role as a biomarker in neurological diseases, and exploring its possible applications in other pathological conditions." (PMID 39995075, 2025). "The potential of peripherin as a biomarker is further supported by recent studies using ultrasensitive detection methods, which have identified elevated peripherin levels in the serum of patients with neurological diseases." (PMID 39995075, 2025). "In addition to commonly used NfL and pNfH, some studies also found potential values of other Nf subunits, i.e., NfM, INA and PRPH as biomarkers in CSF or serum in neurological diseases or injuries." (PMID 34646114, 2021).
endocrinopathy (1 paper, 2025). "Among patients with small fibre/autonomic neuropathies (with or without endocrinopathy) seropositivity for peripherin IgG was found in 33%." (PMID 39995075, 2025).
infection (1 paper, 2015). The state of being infected such as from the introduction of a foreign agent such as serum, vaccine, antigenic substance or organism. "Notably, although contiguous VZV spread with loss of SGC support would be predicted to affect survival of both nociceptive and mechanoreceptive neurons, RT97+ neurons showed selective loss relative to peripherin+ neurons at later times in DRG infection." (PMID 26090802, 2015). "Notably, even though RT97+ neurons had the capacity to restrict VZV replication, neurons expressing this marker showed selective loss relative to peripherin+ neurons at later times in DRG infection when contiguous spread was extensive." (PMID 26090802, 2015). "Because some neurons with large diameter morphology did not exhibit cytopathic changes (black arrow) or express IE63 (black arrow), even where DRG infection was widespread, we next analyzed expression of VZV proteins in sections stained for peripherin and the RT97 marker." (PMID 26090802, 2015). "While observations in VZV-infected DRG suggest that these IE63 functions are not required to interfere with infection in RT97+ neurons, they may be important in peripherin+ neurons." (PMID 26090802, 2015).
infectious disease (1 paper, 2022). A disorder directly resulting from the presence and activity of a microbial, viral, or parasitic agent in humans. "Peripherin seems to also have a role in infectious diseases." (PMID 36499746, 2022).
inherited diseases (1 paper, 2025). "The selective expression of peripherin in certain tissues and the alteration of its levels in biological fluids make it a promising disease biomarker, with a specific focus on acquired or inherited diseases characterized by involvement of the peripheral nervous system." (PMID 39995075, 2025).
peripheral nerve disorders (1 paper, 2023). "We have shown that in peripheral nerve disease, raised levels of neurofilament and peripherin occur in parallel, but that there is an imperfect temporal correlation." (PMID 37435933, 2023). "Peripherin can be used as a biomarker of specific damage to the peripheral nervous system, helping with identification, prognostication and treatment of peripheral nerve diseases." (PMID 37435933, 2023).
PRPH also shares sentences with these, for which no sentence is quoted: schizophrenia (2 papers); spinal muscular atrophy (2); age-related macular degeneration (1); Areflexia (1); autism (1); brain cancer (1); breast carcinoma (1); cognitive decline (1); Cognitive impairment (1); cranial neuropathy (1); diabetic neuropathy (1); frontotemporal dementia (1); Guillain-Barre syndrome (1); Hirschsprung disease (1); leukemia (1); liver cancer (1); macular degeneration (1); mood disorder (1); pattern macular dystrophy (1); psychiatric diseases (1); retinal disease (1); rheumatoid arthritis (1); Stargardt disease (1); vasculitis (1).